HGF (hepatocyte growth factor)
Diseases named in the same sentence as HGF in open-access papers (continued):
Sharing a sentence is not in itself a finding about the gene and the disease.
Obesity (54 papers, 2006 to 2026). Accumulation of substantial excess body fat. "Elevated levels of HGF have also been found to be associated with increased insulin resistance, a marker of severe obesity." (PMID 39184030, 2024). "Increased HGF levels are linked to obesity-related metabolic disturbances that are more prevalent in SCD cases than the controls." (PMID 36142157, 2022). "We also showed an independent and positive association between SCD and HGF, which has previously been linked to obesity and CVD." (PMID 36142157, 2022). "Although the great amount of evidence has suggested that increased levels of HGF are associated with the manifestation of IR, this review has highlighted some of the beneficial effects stemming from HGF activity observed in obesity." (PMID 30214428, 2018). "Regarding obesity-induced IR, which is strongly associated with an inflammatory state, HGF also emerges as a positive factor." (PMID 30214428, 2018). "These gain-of-function and loss-of-function studies demonstrated that the elevated HGF level induced by HFD have protective role against obesity and insulin resistance." (PMID 28273932, 2017). "Previous reports demonstrated that circulating hepatocyte growth factor (HGF) level was associated with obesity and type 2 diabetes." (PMID 28273932, 2017). "Altogether, our previously published studies on HGF/cMET implicated HGF/cMET signaling as a mediator of obesity-driven BBC tumor aggression." (PMID 27057482, 2016). "Using primary murine fibroblasts isolated from mammary glands or tumors, we further reported that obesity increased HGF production by mammary gland normal- and cancer-associated fibroblasts (NAF and CAF)." (PMID 27057482, 2016). "Hepatocyte growth factor (HGF) signaling through its receptor, cMET, is elevated in obesity and is a pro-tumorigenic pathway strongly associated with BBC." (PMID 27057482, 2016). "Taken together, the HGF/c-Met pathway is one potential mechanism that is associated with obesity in mice and humans, as well as BBC samples." (PMID 25072025, 2014). "In summary, our findings of an association between the CYP19A1 gene variants and circulating HGF levels offer a novel mechanism underlying the link between obesity and endocrine-related diseases." (PMID 22848710, 2012). "Circulating HGF levels are also positively associated with risk for obesity-related clinical outcomes including hypertension, type 2 diabetes, and ischemic stroke." (PMID 22848710, 2012). "Moreover, the cytokines IL-18 and HGF showed strong positive associations with overweight and obesity." (PMID 37659013, 2023). "Moreover, increased levels of circulating HGF in people associate with features of cardiometabolic disease, including obesity, risk for type 2 diabetes, and risk for cardiovascular disease." (PMID 36413406, 2023). "HGF is elevated in patients with obesity is linked to hepatocellular carcinoma." (PMID 36038791, 2022). "Importantly, HGF/c-Met expression in normal mammary glands and c-Met in tumors was elevated with obesity and was significantly reversed with weight loss." (PMID 25072025, 2014). "In addition, weight loss reversed obesity-induced HGF/c-Met expression in normal mammary gland compared to mice that remained obese." (PMID 25072025, 2014). "Since HGF stimulates insulin secretion and increases β-cell mass, both in vitro and in vivo, and due to the fact that increased circulating levels of this hormone are associated with obesity, HGF might link insulin resistance and β-cell hyperplasia." (PMID 30214428, 2018). "Furthermore, due the importance of adipose tissue in IR, adipose-derived HGF expression might also have an influence on the obesity associated IR etiology." (PMID 30214428, 2018). "In sum, weight loss significantly blunted the obesity-responsive pro-tumorigenic HGF/c-Met pathway and improved several metabolic risk factors associated with BBC, which together may have contributed to the dramatic reversal of obesity-driven tumor progression." (PMID 25072025, 2014).
Obesity (continued). "Regarding the adipocytokine HGF, increased plasma levels have been observed in individuals with obesity, metabolic syndrome (MetS), and chronic liver diseases." (PMID 41303424, 2025). "Remarkably, excess hepatic PAI-1 in the context of obesity-induced T2DM disrupts HGF activation in the liver, leading to impaired signaling through its receptor that is encoded by the gene MET." (PMID 39825925, 2025). "OPN and HGF are promising biomarkers that can be used to better understand and detect problems related to obesity." (PMID 38574573, 2024). "HGF levels correlate with body mass index and increase during obesity, potentially serving as an early obesity/insulin resistance signal." (PMID 38654922, 2024). "Increased HGF synthesis in adipocytes affects the pathogenesis of insulin resistance and related obesity." (PMID 38574573, 2024). "Our results for hepatocyte growth factor are consistent with previous cross-sectional studies which have reported a positive correlation between obesity and hepatocyte growth factor in serum." (PMID 38290287, 2024). "In a study in mice, however, HGF was found to inhibit diet-induced obesity and to improve insulin resistance." (PMID 37659013, 2023). "In humans, circulating high levels of HGF positively correlate with insulin resistance and glycemic status and were reported to be elevated in obesity, hypertension, and metabolic syndrome." (PMID 36834782, 2023). "On the other hand, there are some beneficial effects of raised HGF levels in obesity, as HGF considerably increases glucose metabolism and transport in myocytes and adipocytes." (PMID 35813634, 2022). "According with reported literature, V-ASCs, isolated from CRC patients with obesity, produce more abundant IL-6 and HGF as compared with S-ASCs, CR-CSphCs, and primary adipose tissue cells (AT)." (PMID 34408135, 2021). "Overall, the existing literature using gain- and loss- of-function studies demonstrate a protective role of the HGF/MET pathway in obesity and insulin resistance by acting on several organs including the liver and skeletal muscle." (PMID 32372975, 2020). "In three independent studies, circulating HGF levels have been shown to be elevated in obesity, diabetes and metabolic syndrome." (PMID 32372975, 2020). "We have found a link between BMR, spleen volume and HGF levels in patients with obesity-related NAFLD." (PMID 31547124, 2019). "Together, these results reinforce the already presented protective role of HGF on glucose metabolism in obesity." (PMID 30214428, 2018). "HGF levels have also been correlated with anthropometric measures of obesity such as waist circumference, body mass index and body fat mass." (PMID 30214428, 2018). "It is becoming clear that hepatocyte growth factor (HGF) is an important component of the pathophysiology of IR, with increased levels in most common IR conditions, including obesity." (PMID 30214428, 2018). "HGF (ENSP00000222390) has also been induced to reveal the linkage between obesity and endocrine diseases." (PMID 29258237, 2017). "HGF is a cytokine secreted from adipocyte tissue, known to increase with hypertension and obesity and most likely regulated by genetic factors." (PMID 28522899, 2017). "Hepatocyte growth factor (HGF) was shown to be secreted by human adipocytes and the production of HGF by adipocytes contributed to its elevated serum level in obesity." (PMID 28915700, 2017). "Definitely, pleiotropic action on insulin targeting organ is involved in the protective role of HGF on HFD-induced obesity and insulin resistance." (PMID 28273932, 2017). "The HFD-induced obesity in wild-type mice treated with HGF-neutralizing antibody showed an exacerbated response to the glucose tolerance test." (PMID 28273932, 2017). "HGF is an excellent candidate mediator of obesity-induced effects on cancer, as serum HGF is elevated in obese individuals and reduced with weight loss." (PMID 27057482, 2016).
Obesity (continued). "This would limit our assessment of the relationships between HGF and the modifying GDM risk factors we evaluated (pre-pregnancy obesity and LTPA)." (PMID 27158627, 2015). "We have previously shown that stromal-derived hepatocyte growth factor (HGF/scatter factor) and its cognate receptor c-Met correlated with obesity-induced BBC tumor onset in nulliparous mice and were reduced with weight loss." (PMID 25354395, 2014). "We have previously reported a potential role for stromal-derived hepatocyte growth factor (HGF) via its cognate receptor c-Met in the etiology of obesity-induced BBC tumor onset and in both human and murine primary coculture models of BBC-aggressiveness." (PMID 25354395, 2014). "Obesity was also shown to elevate mammary gland expression and activation of hepatocyte growth factor (HGF)/c-Met compared to lean controls, a pro-tumorigenic pathway associated with BBC in patients." (PMID 25072025, 2014). "This study shows decreased serum anti-inflammatory miR-146a, increased pro-inflammatory IL-8 and increased HGF (a vascular/insular repair factor) as discriminating markers of failure of glucose control occurring on the background of obesity and dyslipidemia." (PMID 25500583, 2014). "Obesity in 60%-fed mice significantly elevated HGF concentrations in the normal mammary gland compared to mice fed 10% diet (P = 0.01)." (PMID 25072025, 2014). "The reduction in HGFα levels in the context of skeletal muscle may result in impaired glucose metabolism since HGF-targeted delivery to the skeletal muscle improves glucose homeostasis in mice with diet-induced obesity." (PMID 39825925, 2025). "•OPN and HGF are promising biomarkers that can be used to detect problems related to obesity." (PMID 38574573, 2024). "Thus, HGF is involved in β-cells' compensatory responses to conditions characterized by insulin resistance, such as obesity and pregnancy." (PMID 38654922, 2024). "Thus, taxifolin can prevent the systemic effects of obesity in cancer cells by reducing signaling due to adipose-secreted HGF." (PMID 36670988, 2023). "Obesity could increase the levels of various growth factors, such as vascular endothelial growth factor, hepatocyte growth factor and tumor necrosis factor, creating a chronic inflammatory milieu that supports tumorigenesis." (PMID 35069893, 2022). "There is a connection between obesity and elevated serum HGF." (PMID 35813634, 2022). "Consistent with the improved glucose tolerance when overexpressed, a HGF-neutralizing antibody in wild-type mice exacerbated the symptoms of diet-induced obesity and impaired glucose clearance ability, but the tissues responsible for this phenotype were not identified." (PMID 32372975, 2020). "At the best of our knowledge, no research raised a question as to whether BMR can actually be linked to some immune system parameters such as spleen as well as to L-16, IL-12p40 and HGF in obesity-related NAFLD patients." (PMID 31547124, 2019). "Moreover, ezetimibe improves not only lipid profiles, but also atherogenic factors and biomarkers, such as hepatocyte growth factor and insulin resistance, in patients with obesity and hypercholesterolemia." (PMID 30519809, 2019). "On the contrary, in mice HGF improves IR and prevents high-fat-diet-induced obesity." (PMID 31547124, 2019). "These HGF-mediated effects on β-cell proliferation and expansion indicate that this hormone has a crucial role in increased metabolic demand, which is commonly observed in obesity-induced IR." (PMID 30214428, 2018). "Thus, it is quite plausible that the HGF synthesized in human adipose tissue plays an important role in obesity." (PMID 30214428, 2018). "In this experiment using neutralizing antibody against HGF and HGF-Tg mice, we asked whether increased serum HGF is benign or malign factor for obesity and insulin resistance." (PMID 28273932, 2017). "Next, we investigated the mechanism how HGF prevented HFD-induced obesity and insulin resistance." (PMID 28273932, 2017).
Obesity (continued). "Pre-pregnancy overweight/obesity status and LTPA may modify associations of early pregnancy HGF with subsequent GDM risk." (PMID 27158627, 2015). "Overweight/obesity status and LTPA may modify associations of early pregnancy serum HGF with subsequent GDM risk." (PMID 27158627, 2015). "Since pre-pregnancy obesity is a risk factor to GDM, we can contemplate that associations of higher HGF levels with risk of GDM may be exaggerated in the setting of pre-pregnancy obesity, as observed in the current study." (PMID 27158627, 2015). "A report described the relationship between obesity and serum HGF levels." (PMID 25575766, 2015). "Our findings suggest that obesity-driven factors such as HGF/c-Met, insulin, and the leptin:adiponectin ratio may contribute to the onset of obesity-promoted BBCs, and that weight loss prior to tumor onset may prevent tumor progression." (PMID 25072025, 2014). "Furthermore, our results also revealed several common upstream regulators associated with immune regulation and resistance to obesity (IL-4, IL-5, IL-33, CD15, HGF, ANGPT2, VEGFA, and neuropilin 1 [Nrp1]), supporting a critical role of intestinal homeostasis in systemic pathogenesis of obesity." (PMID 36880999, 2023). "Thus, elevated HGF levels in individuals with obesity might primarily be a compensatory mechanism in reaction to (diet-induced) obesity." (PMID 37659013, 2023). "Thus, reinforcing the notion that HGF plays an important role in obesity-mediated IR in muscle." (PMID 30214428, 2018). "However, this compensatory mechanism is insufficient to prevent adipose tissue inflammation and obesity; 2) Additional HGF over expression observed in HGF-Tg mice inhibited HFD-induced obesity and insulin resistance, accompanied by significant reduction of inflammation in gWAT." (PMID 28273932, 2017). "Furthermore, HGF acts as a growth factor for a broad spectrum of tissues and cell types and is extensively reported to participate in regulating high-fat-diet-induced obesity and improve insulin resistance in mice." (PMID 29258237, 2017). "Thus, in this study, we examined whether increased serum HGF is devil or angel for obesity and insulin resistance." (PMID 28273932, 2017). "Indeed, obesity-promoted HGF production by fibroblasts, adipocytes, macrophages, and endothelial cells may be a unique mechanism to increase blood vessel density and alleviate the hypoxia of obese adipose tissue." (PMID 27057482, 2016). "In tumors, HGF protein concentrations were not significantly regulated by obesity or weight loss." (PMID 25072025, 2014). "Interestingly, PAI-1 has been reported to reduce the amount of active HGF, a cytokine that increases glucose transport ex vivo in the skeletal muscle and whose overexpression in this tissue counteracts muscle insulin resistance and improves glucose tolerance in an animal model of obesity." (PMID 39825925, 2025). "NF-κB activation stimulates the transcription of hepatocyte growth factor (HGF), which is a hepatocyte mitogen elevated in sera of patients with NAFLD, obesity, hypertension, and metabolic syndrome." (PMID 36834782, 2023). "CDCP1, FGF23, HGF and IL-6 still had more prominent positive associations with %BF in overweight compared to normal weight subjects and the coefficients did not indicate that the associations were driven by obesity, whereas MCP-1 had a clear positive association with %BF only in the obese group." (PMID 34059769, 2021). "Herein, we assessed if weight reduction through dietary intervention would reverse obesity-induced BBC, and examine important metabolic parameters and the HGF/c-Met pathway." (PMID 25072025, 2014). "Obesity reflects ageneralized proinflammatory state with its increased inflammatorymarkers like C reactive protein, IL-6, IL-8, IL-10, PAI-1,TNF-α, and hepatocyte growth factor." (PMID 21991518, 2011).
Obesity (continued). "We identified the following: 1) HGF expression was increased in insulin target organ, such as liver, SM, and gWAT, in WT mice fed an HFD, and inhibition of HGF by antibody exacerbated HFD-induced obesity, insulin resistance, and impaired insulin signaling." (PMID 28273932, 2017). "Although HGF protein concentrations in tumors were not significantly modified by obesity, similar to our previous findings, c-Met was dramatically elevated with obesity, and significantly blunted to control levels by weight loss." (PMID 25072025, 2014). "Recent familial aggregation studies have reported significant parent-offspring and sibling correlations with HGF levels, independent of age and obesity-related phenotypes, suggesting that HGF secretion is also under genetic control." (PMID 22848710, 2012). "Thus, the balance between the oponents HGF and TGF-β is also altered, which may influence kidney morphology and pathophysiology, possibly contributing to obesity-related nephropathy." (PMID 28536464, 2017). "Thus, HGF is a strong anti-inflammatory growth factor in adipose tissue, and as a consequence, HGF could prevent HFD-induced obesity and systemic insulin resistance." (PMID 28273932, 2017). "Mean levels of growth factors IGF1, HGF, and PDGF-BB remained consistent across individuals with normal weight, overweight and obesity." (PMID 41150772, 2025).